CD4 (CD4 molecule)
Diseases named in the same sentence as CD4 in open-access papers (continued):
Sharing a sentence is not in itself a finding about the gene and the disease.
atherosclerosis (continued). "Our and others' reports demonstrated that CD4+Foxp3+ regulatory T cells play significant roles in suppressing immune responses, inflammations, atherosclerosis, and antitumor immune reactions and promoting tissue regeneration." (PMID 35211628, 2022). "The site of naïve CD4+ T cell activation in the early stage of atherosclerosis remains highly debated." (PMID 35428200, 2022). "The AIM assay showed induction of CD69+CD134+ activation markers on CD4+ T cells, supporting the existence of P210-experienced T cells in humans with atherosclerosis." (PMID 35536648, 2022). "CD4 and CD8 T cell subtypes are implicated in PE, hypertension and atherosclerosis although the complex co-stimulatory and co-inhibitory pathwsays regulating T cell activation in these conditions remains incompletely understood." (PMID 35887949, 2022). "It has been reported that RA patients with extraarticular inflammation or atherosclerosis have prominent CD4+CD28-T cells." (PMID 36483559, 2022). "The converse is also true; stimulation of PD-1 signalling in mice inhibits atherosclerosis by modulating T-cell activity – reducing interferon-gamma producing CD4 + T cells and increasing atheroprotective IL-10 secreting CD4 + T-cells." (PMID 36461057, 2022). "In this study, we assessed the effects of systemic inflammation, microbial translocation (MT), T cell immune activation (IA), and nadir CD4 counts on cardiac function and arterial stiffness as markers of subclinical atherosclerosis in HIV-infected individuals." (PMID 35581554, 2022). "The CD4+ T cell response is also highly involved in the pathogenesis of atherosclerosis and PD-L1hi B cells have previously shown to restrict CD4+ T cell differentiation." (PMID 35187121, 2022). "No research, except for our study on ASO, has been conducted on the relationship of miR-142-3p in CD4+ T cells to atherosclerosis." (PMID 35428200, 2022). "Our immune cell restriction analysis findings show that JAK3 expression is highly correlated with T-follicular helper CD4+T cells, which stimulate atherosclerosis and additional CVDs." (PMID 35844366, 2022). "CD4+ regulatory T cells (Tregs) respond to environmental cues to permit or suppress inflammation, and atherosclerosis weakens Treg suppression and promotes plasticity." (PMID 36139385, 2022). "Of note, the brain of this 83-year-old female also showed subacute infarct, neuronophagia, CD8 + and CD4 + T lymphocytes, and age-related chronic pathology including AD, neocortical Lewy body disease, atherosclerosis, and chronic infarcts (patient #19)." (PMID 36528671, 2022). "Activated CD4+ T cells migrate to atherosclerotic plaques and affect the development of atherosclerosis." (PMID 35428200, 2022). "The immune cell landscape in atherosclerosis was diverse, dominated by M2 macrophages, M0 macrophages, resting CD4 memory T cells and CD8 T cells." (PMID 34729909, 2021). "It suggested a role for the immune system in the development of atherosclerosis, one in which a bigger difference between CD4 count before and after successful cART results in greater vascular inflammation." (PMID 34239489, 2021). "STAT3 has a well-known role in inflammation and immunity, and IL-1R signaling in CD4+ T-cells promotes Th17 immunity and atherosclerosis." (PMID 34630400, 2021). "In line with this, another research group reported that adoptive transfer of CD4+CD25+ Tregs attenuated the development of atherosclerosis in Treg-competent Apoe−/− mice." (PMID 34945203, 2021). "Transfer of WT B cells led to a drastic increase in atherosclerosis due to the infiltration of activated CD4 T cells into atherosclerotic lesions; however, this effect was significantly reduced when MHC-II-deficient B cells were used for adoptive transfer." (PMID 33572939, 2021).
atherosclerosis (continued). "Here, we report that hyperlipidemia induced plasma IL-35 expand the splenic CD4+Foxp3+ Tregs and support the frequencies of infiltrated Tregs in atherosclerotic aortas, which are negatively correlated with the progression of atherosclerosis." (PMID 34622804, 2021). "Interleukin-17-producing CD4+ T cells (Th17 cells) play important roles in the progression of atherosclerosis." (PMID 33981738, 2021). "In atherosclerosis, autoreactive CD4+ T cells with a predominant or partial Treg phenotype in the absence of atherosclerosis and a pathogenic phenotype in established disease have been found in two studies employing MHC-II tetramers in humans and mice." (PMID 33669769, 2021). "Further investigation found that CD4+CD25+Foxp3+ Tregs were significantly decreased in HFD-induced atherosclerosis, and the treatment with rSj-Cys significantly stimulated the proliferation of Tregs in splenocytes." (PMID 34901005, 2021). "Adoptive transfer of CD4+CD25+ Tregs prevents angiotensin II-induced AAA formation in atherosclerosis-prone Apoe−/− mice." (PMID 34945203, 2021). "In contrast, IL-10 has well-described anti-atherogenic properties and is often associated with regulatory T cells, which can suppress activation and proliferation of immune cells during atherosclerosis, including IFNγ-producing CD4+ T cells." (PMID 34790707, 2021). "Together, our results provide convincing evidence that IL-35 promotes CD4+Foxp3+ Treg expansion and impedes atherosclerosis via CCR5-amplified suppressive mechanisms." (PMID 34622804, 2021). "Intravenously administered anti-CD3 monoclonal antibodies, effective in treating autoimmune diabetes in mice and humans, also improve atherosclerosis in mice by regulating Teff immune responses and expanding CD4+CD25+ Tregs." (PMID 34945203, 2021). "Immature tolerogenic DCs, characterized by low expression levels of MHC class II molecule and costimulatory molecules, expand CD4+Foxp3+ Tregs and inhibit Teff responses, contributing to the maintenance of immune tolerance and regulation of atherosclerosis." (PMID 34945203, 2021). "Depletion of CD4 + CD25 + Treg aggravates atherosclerosis in hypercholesterolemic mice, whereas the input of Tregs is protective." (PMID 34915859, 2021). "CD4 positive cell differentiate into various subtypes of helper T cells which have been attributed pro- or anti-inflammatory in atherosclerosis." (PMID 32133374, 2020). "In non HIV-infected patients and animal models, CD4+ cells modulate inflammation and consequently atherosclerosis." (PMID 33143256, 2020). "It has been reported that the water-soluble phenolic compound of Danshen were able to increase CD4 T cell to treat atherosclerosis by modulating the inflammation." (PMID 32020855, 2020). "The results of dynamic analyses showed that Th22 cells, which secrete the majority of IL‐22 among the known CD4+ cells, play a major role in atherosclerosis." (PMID 32022386, 2020). "Although not fully understood, the probable mechanism involves both chronic inflammation, CD4 cell depletion, endothelial dysfunction and atherosclerosis." (PMID 33054784, 2020). "In particular, the presence of atherosclerosis and higher cardiovascular mortality has been described in patients with reduced CD4+ T lymphocytes and detectable viremia." (PMID 33143256, 2020).
atherosclerosis (continued). "For example, the T cell-specific overexpression of CTLA4 reduced atherosclerosis in ApoE−/− mice and limited the numbers of CD4+ T cells and macrophages in the plaque and decreased systemic T cell activation." (PMID 32872393, 2020). "There is compelling evidence pointing to a role for Th1 CD4+ T-cells in promoting inflammation and atherosclerosis in humans." (PMID 33297441, 2020). "We report that M. bovis BCG infection expanded the proportion of circulating CD4+ T cell and Ly6Clow monocytes, and aggravated atherosclerosis formation in murine aorta." (PMID 33391278, 2020). "In particular, CD4+ T cells and their pro- and anti-inflammatory T helper cell subsets have been shown to modulate the pathogenesis of atherosclerosis, as reviewed elsewhere." (PMID 33383733, 2020). "Several lines of evidence support our conclusion that B cells in concert with CD4 T cells promote atherosclerosis." (PMID 31998318, 2019). "In contrast, wildtype B cells transferred into μMT−/− ApoE−/− mice increased atherosclerosis and increased CD4 T cells in lesions including activated and memory CD4 T cells." (PMID 31998318, 2019). "Accumulating evidence demonstrated that the IL-12 cytokine family plays a vital role in atherosclerosis through regulating the activity of CD4+ T cells." (PMID 31093011, 2019). "Immune cells, especially CD4+ T cells, play a central role in the physiological process of atherosclerosis based on their vital roles in the cellular immune network." (PMID 31588227, 2019). "CD4+ T cells were the mostly wildly studied during atherosclerosis and predominant both in human and in mouse atherosclerotic lesions." (PMID 31093011, 2019). "MS patients had opposite cell type distribution in comparison to atherosclerosis, AD and PD patients with higher CD4+ T- and B-cell levels and lower granulocyte levels." (PMID 31827492, 2019). "CD3-Ab treatment was reported to induce rapid regression of established atherosclerosis via reducing CD4+ T cells and increasing the proportion of regulatory T cells (Tregs), which indicated the function of CD3-positive T cells in atherosclerosis." (PMID 31637003, 2019). "B-cells and CD4+ T-cell levels were both reduced while granulocyte levels were increased in atherosclerosis and AD samples as compared to healthy blood samples." (PMID 31827492, 2019). "Our findings suggest that B cell recruitment of CD4 T cells contributes to atherosclerosis development." (PMID 31998318, 2019). "For example, disruption of CD4+CD25+ Tregs with anti CD25 antibodies in ApoE−/− mice accelerates the development of atherosclerosis lesions and increases plaque vulnerability." (PMID 31653058, 2019). "Collectively our results demonstrate key roles provided by B2 cells in recruiting CD4 T cells to arterial lesions in atherosclerosis development." (PMID 31998318, 2019). "Here we report that interaction between B and CD4 T cells augments their atherogenicity to promote lipid-induced atherosclerosis." (PMID 31998318, 2019). "T cell depletion strategies depleted both CD4 and CD8 T cells; the latter also being important in atherosclerosis and antibodies depleting CD4 T cells also deplete CD4+ NKT cells which also contribute to atherosclerosis." (PMID 31998318, 2019). "Proinflammatory IFNγ (interferon γ)-producing CD4+ T cells promote atherosclerosis, whereas CD4+ Tregs prevent it." (PMID 31610723, 2019). "CD4 T cells were first reported as atherogenic cells because CD4 T cell transfer into ApoE−/−scid/scid mice increased atherosclerosis." (PMID 31998318, 2019). "In fact, atherosclerosis progression, the main cause of CVD, is facilitated by an unbalanced interplay of different CD4+ T cell subsets, which promote plaque lesion formation in the vascular bed." (PMID 31299986, 2019). "Here, we addressed the role played by autophagy in DCs during CD4+ T-cell priming/polarization in atherosclerosis." (PMID 31610723, 2019).
atherosclerosis (continued). "In both atherosclerosis and AD, granulocyte levels were increased while B and CD4+ T-cells were decreased." (PMID 31827492, 2019). "Better understanding of the mechanisms involved in the polarization of naive CD4+ T cells in experimental atherosclerosis will help to identify new therapeutic strategies." (PMID 31610723, 2019). "In atherosclerosis, CD4+ Th2 immune responses are considered to be anti-inflammatory due to the secretion and action of IL-4 or IL-5, linked to B cell activation and antibody production." (PMID 30979943, 2019). "Over the last couple of decades, atherosclerosis has been considered a CD4+ T cell-mediated chronic inflammatory disease." (PMID 31093011, 2019). "Later CD28+ CD4+ CD25+ regulatory T cells were found to be a protective CD4 subset in atherosclerosis suggesting that CD28-null CD4 T cells are atherogenic." (PMID 31998318, 2019). "Some studies have investigated a specific Th1 subpopulation, called CD4+CD28null, in cardiovascular diseases such as atherosclerosis and acute coronary syndromes." (PMID 30687720, 2018). "Previous studies demonstrated that the subsets of CD4+ T helper (Th) cells are closely related to vascular diseases, including atherosclerosis and hypertension." (PMID 30258282, 2018). "Low expression level of CD4+CD25+Foxp3+ Tregs was thought to be involved in the development stages of human atherosclerosis." (PMID 29976209, 2018). "We assessed the naïve CD4+ T cell compartment in blood, spleen, and mediastinal lymph node (medLN, the lymph node draining from the trivalve area) as CD4+ T cells can be activated by lipoprotein-derived antigens during atherosclerosis." (PMID 30619297, 2018). "In conclusion, T cell-specific Atg7 deficiency decreased the degree of diet-induced hepatic steatosis and atherosclerosis due to a decrease in numbers of CD4+, CD8+, and NKT cells." (PMID 30619297, 2018). "Hematopoietic ablation of Il27ra accelerated atherosclerosis due to enhanced activation of CD4+ T cells, in particular, Th17 cells, accompanied by increased IL-17A, TNF-α and IL-6 production, CCL2 chemokine expression and accumulation of myeloid cells." (PMID 28536468, 2017). "CD4+ T-cell depletion in these mice reduced atherosclerosis, suggesting a role of TLR9 in regulating CD4+ T cells in atherosclerosis." (PMID 28405010, 2017). "On the other hand, Hsue and colleagues showed that nadir CD4+ cell count <200 cells/μl is an independent predictor of the progression of subclinical atherosclerosis." (PMID 28749986, 2017). "Atherosclerosis reportedly involves the thickening of the artery wall as a result of the infiltration and accumulation of CD4+ T cells, which are involved in plaque formation." (PMID 28241014, 2017). "In mice, MMF slows down the progression of atherosclerosis by inhibiting CD4+ T-cell activation and infiltration to the atherosclerotic lesion." (PMID 29435447, 2017). "Overall our data demonstrate a suppressive role of IL-27R signaling on myeloid cells activation, antigen presentation and interaction with CD4+ T cells, thus positioning IL-27R signaling as an important regulator of immune response in atherosclerosis." (PMID 28536468, 2017). "In fact, CD4+ T cells increase the progression of atherosclerosis in Apolipoprotein E (ApoE) knockout mice." (PMID 28241014, 2017). "Some studies show that atherosclerosis is reduced in immunodeficient mice, and transferring CD4+T cells can reverse the atheroprotective effect of T cell defects, but studies on the CD4-deficient ApoE-/- mice observe the opposite effect." (PMID 29245903, 2017).
atherosclerosis (continued). "CD4 + CD25highFoxP3+ regulatory cells seem to be over-stimulated in the early pre-clinical phase of atherosclerosis and a relationship exists between their frequency and circulating lipids." (PMID 26822994, 2016). "CD4+ T cells have been shown to be important in atherosclerosis and Ang II-induced thrombus formation." (PMID 26379554, 2015). "Accumulating evidence suggests vascular wall chronic inflammation mediated by CD4+ T cells plays a critical role in the development and progression of atherosclerosis." (PMID 25269085, 2014). "We aimed to assess the association between the CD4:CD8 ratio and intima-media thickness (IMT) progression in treated HIV-infected patients as a marker of early atherosclerosis." (PMID 25397469, 2014). "We analyzed the associations between the CD4:CD8 ratio, cardiovascular risk factor and antiretroviral (ARV) treatment and progression of subclinical atherosclerosis assessed using carotid IMT at baseline and after three years." (PMID 25397469, 2014). "In this study, we evaluated the production and function of CD4+ inflammatory and regulatory T cells in atherosclerosis-prone mice." (PMID 25269085, 2014). "Activation, migration and proliferation of CD4+ T cells are critical cellular events in the pathogenesis of atherosclerosis." (PMID 24743945, 2014). "Atherosclerosis is a chronic inflammatory process of the vessel walls, and CD4+ T-cells are peculiar to both human and murine atherosclerotic lesions." (PMID 25092442, 2014). "Considering the importance of adaptive immune on atherosclerosis, another miRNA array in CD4+ T cells from patients with ASO is performed." (PMID 24743945, 2014). "For example, in subclinical atherosclerosis patients, levels of IL-6 are correlated with decreases in naive CD4+ T cells." (PMID 25244034, 2014). "Although the activation and proliferation of CD4+ T cells in arteries are important in atherosclerosis, migration of these CD4+ T cells from circulation to atherosclerotic lesions is the prerequisite in CD4+ T cell-mediated effects on atherogenesis." (PMID 24743945, 2014). "We found that the hyperactivity and unresponsiveness to Treg-mediated suppression of inflammatory CD4+ T cells occurred in the progression of atherosclerosis, though Treg cells were present in very large numbers and fully functional." (PMID 25269085, 2014). "The best-described CD4+ Treg cells in experimental atherosclerosis are the naturally occurring CD4+CD25+ Treg cells, which have been shown to be continuously produced within the thymus." (PMID 24385687, 2013). "The roles of four CD4+ Th cell lineages, Th1, Th2, Th17, and Treg cells, in atherosclerosis are widely studied." (PMID 24453425, 2013). "We measured Th cells as a percentage of lymphocytes by flow cytometry using CD4 staining (%CD4) in 917 participants of the Multi‐Ethnic Study of Atherosclerosis." (PMID 23688675, 2013). "We examined cross-sectional relationships of circulating CD4+ naive and memory T cells with biomarkers of inflammation, serologies, and subclinical atherosclerosis in 912 participants of the Multi-Ethnic Study of Atherosclerosis (MESA)." (PMID 24009662, 2013). "CD4+LAP+ Treg cells are a novel subset of Tregs that have been found to ameliorate atherosclerosis in ApoE−/− mice, and these cells also exist in humans." (PMID 24385687, 2013). "Other subsets of CD4+ Treg cells, such as T-helper cell type 3 (Th3) and type 1 Treg (Tr1) cells, were also shown to attenuate atherosclerosis in apolipoprotein E-knockout mice." (PMID 24385687, 2013). "Recently, it has been reported that CD4+ T-helper cells were involved in the development of atherosclerosis." (PMID 24312440, 2013). "In mice, adoptive transfer studies of CD4+ T cells specific to oxLDL have shown that Th1 cell responses play an important role in promoting atherosclerosis." (PMID 23805273, 2013).